HOXD-AS2 (HOXD cluster antisense RNA 2)
Gene: Long non-coding RNA gene on chromosome 2 (176,121,611 to 176,137,098, reverse strand). Ensembl gene ENSG00000237380.
Diseases named in the same sentence as HOXD-AS2 in open-access papers:
HOXD-AS2 is named in the same sentence as 6 diseases in open-access papers, as found by Europe PMC text mining. Sharing a sentence is not in itself a finding about the gene and the disease. The quoted sentences say what the papers report.
glioma (7 papers, 2020 to 2024). A benign or malignant brain and spinal cord tumor that arises from glial cells (astrocytes, oligodendrocytes, ependymal cells). "Our studies reveal the molecular mechanism explaining why HOXD-AS2 was specifically overexpressed in gliomas and provide a theoretical basis for the future of HOXD-AS2 as a potential molecular diagnostic marker." (PMID 35269968, 2022). "LncRNA HOXD‐AS2 was reported to be highly expressed in glioma and associated with glioma grade and poor prognosis." (PMID 34802389, 2021). "HOXD-AS2 promoted glioma progression, and the expression levels of HOXD-AS2 were associated with glioma grade and poor prognosis." (PMID 32793467, 2020). "Our results indicated that elevated HOXD‐AS2 was associated with poor prognosis in glioma." (PMID 37308741, 2023). "Furthermore, we validated and indicated that elevated HOXD‐AS2 associated with poor prognosis in gliomas of different pathological grades and it was promising to be a prognostic factor." (PMID 37308741, 2023). "Our results indicated that HOXD‐AS2 might affect cellular response to DNA damage caused by therapeutic agents, consequently, it might regulate temozolomide sensitivity in glioma." (PMID 37308741, 2023). "To test whether the high expression of HOXD-AS2 in gliomas is caused by copy number variations (CNVs), we observed CNVs at the HOXD-AS2 locus by the database cBioportal." (PMID 35269968, 2022). "Subsequently, we discriminated all glioma samples into two groups of high and low HOXD‐AS2/IGF2BP2 expression in CGGA database, then GSEA and GSVA analysis were conducted to identify functional significance between groups." (PMID 37308741, 2023). "Considering that HOXD‐AS2 was the most upregulated member among them and growing studies revealed its implications in glioma, it deserves an investigation in depth." (PMID 37308741, 2023). "Our study explains why HOXD-AS2 was specifically up-regulated in gliomas, helps to understand the molecular characteristics of gliomas, and provids insights for the search for specific markers in gliomas." (PMID 35269968, 2022). "We previously found that lncRNA HOXD Cluster Antisense RNA 2 (HOXD-AS2) was up-regulated in glioma cells by lncRNA microarray." (PMID 35269968, 2022). "HOXD-AS2 can affect the invasion and apoptosis of gliomas by targeting miR-3681-5p and activating the metastasis associated in lung adenocarcinoma Transcript 1 (MALT1) through competing endogenous RNA (ceRNA) mechanism." (PMID 35269968, 2022). "The results demonstrated that the expression of c-Myc, cyclin D1, cyclin A, and E2F1 decreased after knocking down TFE3, suggesting that the TFE3-mediated overexpression of HOXD-AS2 promoted the cell cycle progression in glioma cells." (PMID 35269968, 2022). "It is expected to be a new marker for molecular diagnosis of gliomas, but little is known about HOXD-AS2." (PMID 35269968, 2022). "We have previously reported that lncRNA HOXD-AS2, which is specifically up-regulated in gliomas, can activate cell cycle and promote the development of gliomas." (PMID 35269968, 2022). "The report, which shows the oncogenic effect of miR-661 in gliomas, is consistent with our studies and further confirms the negative regulation of HOXD-AS2 and miR-661." (PMID 35269968, 2022). "HOXD-AS2, as a kind of lncRNA that is specifically up-regulated in gliomas, has its own significance and value in research." (PMID 35269968, 2022). "To explore the reason of this phenomenon, we analyzed the upstream mechanism of HOXD-AS2 in gliomas." (PMID 35269968, 2022). "It has also been found that the activation of the transforming growth factor beta (TGF-β) signaling pathway can up-regulate HOXD-AS2 in high-expressed MGMT glioma cells." (PMID 35269968, 2022). "Our study showed that silencing lncRNA HOXD-AS2 significantly inhibits the cell proliferation and tumorigenesis of glioma cells, and HOXD-AS2 can regulate the expression of MALT1 by serving as a molecular sponge of miR-3681-5p." (PMID 34802389, 2021).
glioma (continued). "Although a few studies demonstrated the role of HOXD-AS2 in cell cycle regulation and glioma progression, the molecular mechanism by which HOXD-AS2 modulates the aggressiveness of GBM remain to be fully investigated." (PMID 34802389, 2021). "LncRNA HOXD‐AS2 was previously reported to be highly expressed in glioma as compared to normal astrocyte cell lines or tissues." (PMID 34802389, 2021). "We subsequently investigated and explored the potential functions of HOXD‐AS2 in glioma." (PMID 37308741, 2023). "Bio‐informatic analysis was performed to explore potential functions of HOXD‐AS2 in glioma." (PMID 37308741, 2023). "The cell cycle, which is regulated by HOXD-AS2, can promote the development of glioma." (PMID 36980973, 2023). "Previous results revealed that IGF2BP2 bound with HOXD‐AS2 and affected its expression, implying that whether HOXD‐AS2/IGF2BP2 genes' highly expression aggravated glioma progression." (PMID 37308741, 2023). "HOXD‐AS2 is a potential prognostic biomarker in glioma and whether exploring this feedback loop will provide a novel therapeutic candidate deserves further expectations." (PMID 37308741, 2023). "The RT‐qPCR assays revealed that HOXD‐AS2 was remarkably upregulated in glioma cells." (PMID 37308741, 2023). "The results confirmed it was specific that TFE3 mediated HOXD-AS2 in gliomas." (PMID 35269968, 2022). "Overall, these results indicated that HOXD-AS2 upregulation might play a critical role in the development and progression of gliomas." (PMID 35269968, 2022). "But the expression of HOXD-AS2 was lower in gliomas with 1p19q co-deletion." (PMID 35269968, 2022). "Next, we considered whether the maintenance of overexpression of HOXD-AS2 in gliomas was related to the regulation of RNA stability." (PMID 35269968, 2022). "This phenomenon suggested that HOXD-AS2 might play an important role in the development of gliomas." (PMID 35269968, 2022). "Knockdown of HOXD‐AS2 by inducing cell‐cycle G1 arrest could inhibit glioma cell growth." (PMID 33330110, 2020). "HOXD‐AS2 (HOXD cluster antisense RNA 2) is a lncRNA transcript in HOX (homeobox) gene locus and growing studies reported that HOXD‐AS2 exerts its functions in glioma progression." (PMID 37308741, 2023). "The data above demonstrated that HOXD-AS2 was induced by TFE3 and H3K27ac in glioma cells." (PMID 35269968, 2022).
glioblastoma (5 papers, 2022 to 2024). The most malignant astrocytic tumor (WHO grade IV). "It is worth mentioning that we did not prioritize the study of the downstream regulatory mechanism but focused on exploring the cause of the specific overexpression of HOXD-AS2 in glioblastomas." (PMID 35269968, 2022). "Therefore, underlying mechanisms of HOXD‐AS2 affecting the malignant behaviors of glioblastoma deserve an in‐depth investigation." (PMID 37308741, 2023). "STAT3 can also enhance the expression of HOXD-AS2 through transcriptional activation, forming a positive feedback loop and reducing the sensitivity of glioblastoma to TMZ." (PMID 38967893, 2024). "In summary, our study described a HOXD‐AS2‐STAT3 positive feedback loop which attenuates TMZ sensitivity in glioblastoma and it revealed clinical implications involving HOXD‐AS2 and TMZ sensitivity." (PMID 37308741, 2023). "Our results demonstrated that HOXD‐AS2 attenuated the temozolomide sensitivity of glioblastoma in vivo." (PMID 37308741, 2023). "Then, we confirmed that HOXD-AS2 promoted the proliferation of glioblastoma cells and the cell cycle progression; we also demonstrated that the growth of tumors was significantly constrained when silencing HOXD-AS2 in vivo." (PMID 35269968, 2022). "Then, we used The Cancer Genome Atlas (TCGA) and The Genotype-Tissue Expression (GTEx) data and found that HOXD-AS2 was specifically up-regulated in glioblastomas and low-grade gliomas (LGG) compared to other cancers." (PMID 35269968, 2022). "It was found that only TFE3 could stably regulate the expression of HOXD-AS2 in two glioblastoma cell lines, LN229 and A172." (PMID 35269968, 2022). "Therefore, we hypothesized that TFE3 was the transcription regulator upstream of HOXD-AS2 in glioblastomas." (PMID 35269968, 2022). "Based on our previous work, HOXD-AS2 could promote cell cycle in glioblastomas." (PMID 35269968, 2022). "We thus presumed whether HOXD-AS2 is aberrantly transcriptionally activated in glioblastomas." (PMID 35269968, 2022). "The result demonstrated that the expression of HOXD-AS2 was high in LN229 and A172; thus, we mainly chose these two glioblastoma cell lines for the subsequent study." (PMID 35269968, 2022).
tumor (2 papers, 2021 to 2023). "HE staining of mice brain sections also confirmed that combination of TMZ and HOXD‐AS2 knockdown significantly inhibited the tumor growth, which was consistent with previous bioluminescent imaging." (PMID 37308741, 2023). "The knockdown of HOXD-AS2 significantly suppressed the tumor growth, as revealed by the impaired increase of tumor volume and reduced tumor weight in si-HOXD-AS2 group." (PMID 34802389, 2021). "We further compared HOXD-AS2 expression in 92 pairs of GBM patient GBM patient sample and the adjacent normal tissues by qRT-PCR, which validated the upregulation of HOXD-AS2 in GBM tumor tissues." (PMID 34802389, 2021). "Consistent with a previous report, HOXD-AS2 was remarkably upregulated in tumor tissues (p = 4.07E-51)." (PMID 34802389, 2021). "Importantly, in vivo experiments further confirmed that the knockdown of HOXD-AS2 impaired the tumor growth." (PMID 34802389, 2021). "Chi-square test demonstrated that a high expression level of HOXD-AS2 was also significantly associated with TNM staging of GBM tumor, lymphatic metastasis and vascular invasion, but not with gender or age." (PMID 34802389, 2021). "We found that HOXD-AS2 was significantly upregulated in GBM tissues, which was validated in GBM patient tumor samples and cell lines." (PMID 34802389, 2021). "HOXD-AS2 was found to be significantly up-regulated in GBM tissues, which was further confirmed in GBM patient tumor samples and GBM cell lines." (PMID 34802389, 2021). "Importantly, we further analyzed the correlation of expressions between HOXD-AS2 and MALT1, as well as miR-3681-5p and MALT1, in 92 GBM tumor samples." (PMID 34802389, 2021). "In addition, analysis of HOXD-AS2 expression in the GBM sample (n = 163) and normal tissue (n = 207) in GEPIA database also revealed the significant upregulation of HOXD-AS2 in tumor tissues." (PMID 34802389, 2021). "Spearman correlation further showed that there was a significant positive correlation between MALT1 and the expression of HOXD-AS2 in GBM tumor samples, and the expression of miR-3681-5p in tumor tissues showed a negative correlation with MALT1 and HOXD-AS2." (PMID 34802389, 2021). "Interestingly, we found that the tumor foci with the lowest HOXD‐AS2 expression (Foci D) showed no recurrent neoplasm, whereas the tumor foci with higher HOXD‐AS2 expression (Foci A, B, and C) manifested obvious recurrences, suggesting that HOXD‐AS2 might play an important role in chemo‐resistance." (PMID 37308741, 2023).
HOXD-AS2 also shares sentences with these, for which no sentence is quoted: cancer (2 papers); gastric cancer (1); low grade glioma (1).